Y_RNA (Y RNA )
Gene: Miscellaneous RNA gene on chromosome 12 (101,446,825 to 101,446,932, forward strand). Ensembl gene ENSG00000206929.
Homologues: Orthologues: chimpanzee Y_RNA (98% identical). Paralogues in human: RNY1P5 (83% identical), Y_RNA (83% identical), Y_RNA (82% identical), Y_RNA (81% identical), Y_RNA (80% identical), Y_RNA (79% identical), RNY1 (78% identical), Y_RNA (78% identical), RNY1P6 (77% identical), Y_RNA (77% identical), RNY1P1 (76% identical), RNY1P2 (76% identical), and 94 more.